CTLA4 (cytotoxic T-lymphocyte associated protein 4)
Diseases named in the same sentence as CTLA4 in open-access papers (continued):
Sharing a sentence is not in itself a finding about the gene and the disease.
cancer (continued). "When CTLA-4 is bound to another protein called B7, it helps keep T cells from killing other cells, including cancer cells." (PMID 36982144, 2023). "Nonetheless, the epithelial cancer cells were highly sensitive to the anti-PD-L1 or anti-CTLA-4 immunotherapy, whereas the mesenchymal breast-cancer cells were more resistant to these treatments." (PMID 37111629, 2023). "For example, among all cancer types, anti-CTLA-4 drugs have the highest objective radiographic response of 15% in advanced metastatic melanoma." (PMID 37251920, 2023). "Recently, it was discovered that cancer cells can ectopically express CTLA4, in this case due to copy number gains (amplification)." (PMID 36754910, 2023). "Currently, immune checkpoint inhibitors (ICIs) targeting CTLA4 or PD-1/L1 have been shown to provide survival advantage in some treatment-refractory malignant tumors." (PMID 37198617, 2023). "Immune checkpoint inhibitors (ICI) are monoclonal antibodies that block these pathways by binding to PD-1/L1 or CTLA-4 and enhance the immune response against cancer cells and have demonstrated ground-breaking results in several cancers." (PMID 37464378, 2023). "In the past decade, the use of checkpoint inhibitors (CDK inhibitors, PD-[L]1 inhibitors, and CTLA4 inhibitors) has increased in cancer treatment and they have been proven to be effective for improving patients’ survival in a wide range of malignant diseases." (PMID 37229565, 2023). "Cancer cells can downregulate the immune response by exploiting CTLA-4, and this forms the basis of targeting CTLA-4 with monoclonal antibodies such as ipilimumab." (PMID 37842236, 2023). "Considering the well-known indicative powers of PDL1 and CTLA4 for immunotherapeutic response in cancers and their prognostic values in OC, we also examined the correlations between CCI and the expression of them." (PMID 37409345, 2023). "Cancer immunotherapy, particularly immune-checkpoint inhibitors (ICI) targeting cytotoxic T-lymphocyte-associated antigen 4 (CTLA-4) and programmed death 1 (PD-1) inhibitory immune checkpoints, has transformed the management of advanced cancers." (PMID 36806616, 2023). "CTLA-4 and PD-1, which have been widely studied in malignant tumors, can be converted into immune regulation of TME." (PMID 37217993, 2023). "The engagement of co-inhibitory checkpoint molecules such as CTLA-4 and PD-1 by their respective counterparts can block T cell expansion and activation, culminating in the immune evasion of cancer cells." (PMID 37767098, 2023). "The impact of CTLA-4 and PD-1 blockers drastically changes the treatment outcomes of advanced human cancers." (PMID 37370399, 2023). "Are there different cancer cell-killing T cells that are activated by CTLA-4 inhibition versus those that are activated by PD-L1 inhibition?" (PMID 37511873, 2023). "As the first identified immune checkpoint, anti-CTLA-4 treatment indeed makes great progress in neoadjuvant immunotherapy of cancer." (PMID 37691932, 2023). "CTLA-4 has emerged as a critical immune checkpoint receptor with implications for immune evasion by cancer cells in various cancer types, including CRC." (PMID 37576892, 2023). "Serum levels of sCTLA-4 are high in several cancers, but it has only recently been identified to have an immunosuppressive capacity like recombinant CTLA4-Ig, an inhibitory costimulatory modulator used to treat rheumatoid arthritis." (PMID 36980582, 2023). "This article will summarize BsAbs targeting CTLA-4, their applications in cancer immunotherapy, and relevant clinical trial advances." (PMID 37441075, 2023). "ICIs work by unblocking the inhibitory signaling effect of immunomodulatory receptors expressed by immune or cancer cells (such as CTLA‐4 and PD‐1 or PD‐L1), which usually allow cancer cells to escape destruction." (PMID 36748568, 2023).
cancer (continued). "Cancers can evade the immune response and influence immunotherapy by means of immune checkpoint genes, such as PD-L1 (programmed death-ligand 1), PD-1 and CTLA-4." (PMID 36717836, 2023). "Some studies have suggested that CTLA-4 expression positively correlates with cancer severity and prognosis." (PMID 36894965, 2023). "The high correlations between the expression of B7-H3 and CTLA-4 and cancer cell activity can be used to evaluate their potential usefulness as prognostic predictors or immunotherapy targets." (PMID 36894965, 2023). "Cancer immunotherapy with immune checkpoint inhibitors, such as those targeting CTLA-4 and PD-1/PD-L1, has now revolutionized the field of oncology by prolonging survival of patients with rapidly fatal cancers." (PMID 37120591, 2023). "In the context of cancer immunotherapy, antibodies directed against the inhibitory co-stimulatory molecule CTLA4, such as ipilimumab, are used to augment the immune response against tumor-associated peptides." (PMID 36672615, 2023). "A pioneering instance of checkpoint protein inhibition materialized through antibody-mediated blockade of CTLA-4, demonstrating efficacy in cancer immunotherapy." (PMID 37667784, 2023). "Subsequently, the research strategies to overwhelm the resistance of cancer cells seem to be heading toward an intensified strategy comprising better combination with different agents such as PD-1 plus CTLA-4 blockades." (PMID 37720344, 2023). "Antibodies against PD-1, PD-L1, and CTLA-4 have been introduced against various types of cancers by counteracting immune checkpoints and enhancing immune attacks." (PMID 37525297, 2023). "It was shown that blocking VISTA in combination with CTLA-4 and PD-1 showed a synergistic effect and prevented the development of resistance to therapy in cancer patients." (PMID 37936192, 2023). "The nobel prize in physiology or medicine in 2018 recognized the discovery of immunological checkpoints, such as programmed cell death protein 1 (PD-1) and CTLA-4, and their significance in cancer immunology." (PMID 37692610, 2023). "Nowadays, ICIs, such as programmed cell death-1(PD-1), programmed cell death-Ligand 1 (PD-L1), and cytotoxic T lymphocyte-associated antigen-4 (CTLA-4), represent the most promising cancer treatment." (PMID 36969026, 2023). "Immune checkpoint inhibitors (ICIs)‐targeting CTLA4 and PD1 constitute a promising class of cancer treatment but are associated with several immune‐related adverse events (irAEs)." (PMID 36968348, 2023). "As shown in NSCLC, increased degree of CD8+ T cell exhaustion is correlated with increased PD-1 expression and the co-expression of additional co-inhibitory receptors, such as TIM-3, TIGIT, and CTLA-4 at later stages of cancer progression." (PMID 37377970, 2023). "Immunotherapy with Immune Checkpoint Inhibitors (ICI), such as anti-PD-1/PD-L1 and anti-CTLA-4 antibodies, is at the top of interest in cancer research and is now the standard of care for the treatment of several cancers." (PMID 36835456, 2023). "The discovery and clinical application of PD-1 (Programmed cell death 1), PD-L1 (Programmed cell death ligand 1), and CTLA-4 (Cytotoxic T lymphocyte antigen 4) and their inhibitors have introduced novel therapeutic approaches for combating malignant tumors." (PMID 37926852, 2023). "In parallel, bispecific antibodies targeting two immune checkpoints, such as PD-1 or CTLA-4, are currently under development, and will be tested in clinical trials enrolling patients with different cancers, including EC and CC (NCT03517488)." (PMID 37046702, 2023). "The effects of checkpoint inhibitors (PD-1/PD-L1 and CTLA-4) on the microbiota have also been described in multiple reports and cancer mouse models." (PMID 38147032, 2023). "Immune checkpoint molecules such as PD-1, PD-L1 and CTLA4, which are targets for cancer immunotherapy, play an important role in maintaining self-tolerance and modulating the cancer immune response." (PMID 38067407, 2023).
cancer (continued). "In recent years, traditional ICB therapies, such as anti-PD-1/-L1 and -CTLA4, have shown improved antitumor efficacy in some patients with cancer." (PMID 37190154, 2023). "Allison renamed the molecule as Cytotoxic T-lymphocyte Antigen 4 (CTLA4) and realized that cancer cells use the molecule to evade the immune system." (PMID 36661747, 2023). "Studies have found that anti-CTLA-4 therapy brings clinical benefit to cancer patients by depleting Tregs and activating T Cells." (PMID 37333498, 2023). "We next examined the associations of TLR4 expression with 8 immune checkpoints (PD-L1, CTLA4, HAVCR2, LAG3, PDCD1, PDCD1LG2, SIGLEC15, and TIGIT), and TLR4 expression was widely associated with the 8 immune checkpoints in most cancer types." (PMID 37576399, 2023). "High PD-L1/CTLA4 expression levels, high IPS scores, and a greater number of cancer gene mutations have been established as solid predictive biomarkers for patients who are more likely to benefit from immunotherapy." (PMID 36969851, 2023). "Cytotoxic T lymphocyte‐associated antigen 4 (CTLA‐4), programed death 1 (PD‐1), and PD‐L1 were positively associated with ANLN expression in multiple cancers, including BRCA, KICH, KIRC, LIHC, PRAD, and THCA." (PMID 36030492, 2023). "After the success in targeting CTLA-4 during cancer, many antibodies have been designed to disturb the PD-1 axis for a similar purpose." (PMID 39086690, 2023). "In recent years, immune checkpoint inhibitors (ICIs), including anti-programmed cell death -1/programmed cell death ligand-1 (PD-1/PD-L1) and anti-cytotoxic T lymphocyte-associated antigen-4 (CTLA-4) agents, have revolutionized the management of cancer." (PMID 38187399, 2023). "Blocking CTLA-4 and PD-1 with therapeutic antibodies was found to provide survival benefit to cancer patients by rejuvenating the anti-tumor response of CD8+ cytotoxic T-lymphocytes." (PMID 37345111, 2023). "The numbers of PD-L1+ CD4+T, CTLA-4+ CD4+T, PD-L1+ CD8+ T, and CTLA-4+ CD8+ T cells increased as the cancer stage increased." (PMID 37153541, 2023). "Monoclonal antibodies targeting the immune checkpoints CTLA-4, PD-1 and PD-L1 have demonstrated promising clinical efficacy in several cancers, with subsets of patients deriving durable clinical responses." (PMID 37627206, 2023). "Expression of PD-L1 is a clinically recognized indicator for anti-PD-1/PD-L1 therapy in cancer patients, while CTLA-4 is another potential target for immune checkpoint inhibitor (ICI) therapy." (PMID 36969851, 2023). "The Food and Drug Administration (FDA) has approved six inhibitors of the programmed cell death protein pathway (PD1/PD-L1) and an inhibitor of the CTLA-4 for use in treating various cancers." (PMID 36911744, 2023). "Anti-CTLA-4 antibodies have shown efficacy in multiple types of cancers as monotherapy or in combination with other ICIs, especially the anti-PD-1 antibody." (PMID 37790929, 2023). "Currently, cancer immunotherapy by targeting inhibitory receptors such as CTLA-4 and PD-1/L1, and their combination by antagonist antibodies, has been well established." (PMID 37334375, 2023). "Ipilimumab, an anti-CTLA-4 blocking antibody, was the first immune checkpoint inhibitor to be tested and has been approved for treating cancer patients." (PMID 37781078, 2023). "Other PD1 or PDL1 blockers, including ipilimumab (anti-CTLA4 monoclonal antibody), which can regulate adaptive immune functions were shown to stop cancer progression." (PMID 37903125, 2023). "Immune therapies, specifically ICB that target CTLA-4 (a T-cell activation suppressor), can revitalize the immune system's prowess to decimate cancer cells, potentially prolonging patient survival." (PMID 38017020, 2023). "According to the principle of immunotherapy, some immune checkpoints such as PD1/PD-L1 and CTLA4, can be targeted by inhibitors to enhance anti-cancer immunoreaction." (PMID 37543645, 2023).
cancer (continued). "In recent years, treatment with ICIs has steadily improved, and the use of antibodies against PD-1, PD-L1, and CTLA-4 alone, as well as in combinations, has achieved promising results in the treatment of cancer patients." (PMID 36902442, 2023). "Immune checkpoint blockade (ICB) therapy targeting cytotoxic T-lymphocyte-associated protein 4 (CTLA-4) and programmed death protein 1 (PD-1)/programmed death-ligand 1 (PD-L1) has garnered breakthrough therapeutic outcomes in the realm of cancer treatment." (PMID 37945606, 2023). "Anti-CTLA4 agents trigger the immune response of cancer since their PD-L1 (B7-H8) and PD-L2 (B7-DC) ligands are expressed in several tumor types." (PMID 37240983, 2023). "In particular, immune checkpoint antagonists, such as monoclonal antibodies specific for PD-1, PD-L1, and CTLA-4, have revolutionized cancer therapy." (PMID 36765715, 2023). "Immunotherapy-based immune checkpoint blockade targeting PD-1 and CTLA-4 is gradually becoming the candidate treatment for different cancers." (PMID 37341998, 2023). "Some immune checkpoint inhibitors, such as anti-CTLA-4 and anti-PD-L1/PD-1, have been demonstrated in helping to eliminate cancer cells." (PMID 37434155, 2023). "Anti-CTLA therapy works by blocking the CTLA-4 inhibitory signal, which can help activate T cells and enhance their ability to recognize and attack cancer cells." (PMID 37376141, 2023). "Studies have shown that the combined blockade of PD1 and CTLA4 achieves better prognosis improvement compared to monotherapy in several cancer types." (PMID 37600707, 2023). "Cancer cells can exploit this mechanism by upregulating CTLA-4 expression, thereby, suppressing the immune response against them." (PMID 37370565, 2023). "Because CTLA4 acts is a different stage of the cancer immunity cycle compared to PD1, inhibiting both checkpoints is synergistic, with anti-PD1/anti-CTLA4 combination therapy yielding improved clinical benefit relative to anti-PD1 monotherapy." (PMID 36183010, 2023). "The focus extends to the role of immune checkpoint inhibitors in cancer therapy, including CTLA-4, PD-1, and PD-L1 targeting antibodies." (PMID 38136253, 2023). "Successes in therapeutic targeting of PD-1 and CTLA-4 pathways in T lymphocytes are viewed as clinical evidence supporting the notion of cancer surveillance by cells of the adaptive immune system akin to that of pathogens." (PMID 37127830, 2023). "CTLA-4 and PD-1 proteins were overexpressed in both immune T-cells and various cancers such as melanoma, ovarian, breast, prostate, and pancreatic." (PMID 36813833, 2023). "Immune checkpoint inhibitors (ICIs) have changed the landscape of management of several cancers harnessing anti-tumor adaptive immunity by inhibiting key immune system inactivators such as CTLA-4, PD-1, and PDL-1." (PMID 38045806, 2023). "This review summarizes BsAbs targeting CTLA-4, their applications in cancer immunotherapy, relevant challenges, and clinical trial advances." (PMID 37441075, 2023). "Recent advancements in our knowledge about immune checkpoint receptors, CTLA-4, and PD-1 in cancer immunogenicity and their inhibition led to a paradigm shift in cancer treatment strategies." (PMID 37175653, 2023). "Immunotherapy has dramatically improved cancer treatment, for instance through CTLA4 and PD-1 inhibition." (PMID 37393293, 2023). "ICB therapy is regarded as a milestone in cancer immunotherapy, particularly the anti-CTLA4, anti-PD-1, and anti-PD-L1 drugs." (PMID 38041084, 2023). "Immune checkpoint inhibitors blocking CTLA-4/B7 or PD-1/PD-L1 pathways have greatly prolonged the survival of patients with different cancers." (PMID 36810034, 2023). "Combining the CTLA-4/B7 axis blockade, as an auxiliary axis, with PD-1/PD-L1 axis blockade, has become a new direction of cancer immunotherapy." (PMID 37926852, 2023). "On the other hand, studies show that VISTA contributes to developing resistance to immunotherapy with anti-CTLA-4 and -PD-1 in cancer patients." (PMID 37936192, 2023).
cancer (continued). "In a subset of cancer patients with a poor prognosis, the inhibition of PD-1 and CTLA-4 has increased their progression-free survival." (PMID 37600822, 2023). "ICI’s clinical impact on cancer therapy has been so far very relevant: in the past 10 years, eight immune checkpoint blockers against CTLA-4, PD-1, or PD-L1 have been approved for clinical use in more than 85 oncology indications." (PMID 37048617, 2023). "Immune checkpoint blocking therapy promotes a long-lasting anti-cancer response by releasing a block in the immune system including include anti-PD-1, anti-PD-L1, and anti-CTLA4 therapy." (PMID 37251370, 2023). "In the current study, increased nitration after anti-CTLA-4 therapy is associated with prolonged RFS, whereas, in most cancer studies, increased nitration is associated with immune suppression and disease progression at a single time point." (PMID 36980641, 2023). "ICI targeting the PD-1 and CTLA4 immune checkpoints on CD8 T cells or their counter-receptors have become the standard of care for treating immunogenic cancer, such as cutaneous melanoma, but many patients fail to respond." (PMID 36768931, 2023). "It is important to note that the main immune checkpoints described to date (PD1, PDL1, CTLA4) have exactly the same profiles for most cancers." (PMID 38117000, 2023). "Immunotherapy drugs targeting PD-L1 and CTLA-4 are playing an increasingly critical role in the treatment of malignant tumors." (PMID 37063853, 2023). "Anti-CTLA-4 therapies, such as ipilimumab, act by binding to and blocking the function of CTLA-4, thereby enhancing the immune response against cancer cells." (PMID 37031434, 2023). "Anti-CTLA-4 monoclonal antibodies such as ipilimumab bind CTLA-4 to shut down inhibitory signals, enabling CTLs to persist with their cytotoxic activities against cancer cells." (PMID 37064017, 2023). "In recent years, CTLA-4 has become a popular target for cancer immunotherapy in which blocking CTLA-4 can restore T-cell function and enhance the immune response against cancer." (PMID 37110545, 2023). "Recent years, PDCD1 (PD-1), CD274 (PD-L1) and CTLA4 have been confirmed to act as immune checkpoints and can prevent the immune system from killing cancer cells by inhibiting autoimmunity." (PMID 36845098, 2023). "As we all know, after anti-programmed cell death protein 1/programmed cell death ligand 1 (PD-1/PD-L1) got satisfying results in most cancers, CTLA-4 has also made breakthroughs in the immunotherapy of various tumors." (PMID 37064147, 2023). "Noteworthy, PD-1 and CTLA-4 are important cancer immunotherapy targets broadening the potential range of action of these EVs." (PMID 37507751, 2023). "These are antibodies that block immune checkpoint proteins (CTLA-4 and PD-1/PD-L1), molecules that help cancer cells prevent the immune system from attacking them." (PMID 38202123, 2023). "CTLA-4/OX40 (ATOR-1015), and PD-L1/CTLA-4 (KN046) bi-specifics are currently in trial for use in cancer." (PMID 38077329, 2023). "Allison created an antibody that blocked the interaction of CTLA4 with its ligand and observed that mice injected with the antibody were able to eliminate cancer using their immune system." (PMID 36661747, 2023). "The exploration of antibodies or inhibitors aimed at CTLA4 has shown encouraging results in cancer treatment." (PMID 37691924, 2023). "Subsequently, clinical trials evaluated fully human anti-CTLA-4 blocking antibodies in patients with advanced cancers, revealing a durable response in a certain proportion of patients, irrespective of the relatively high frequency of associated toxicity." (PMID 37614504, 2023). "It was reported that checkpoint inhibitors targeting CTLA-4 and PD-1/PD-L1 made a breakthrough in cancer treatment, which achieved impressive clinical responses." (PMID 37533738, 2023).